HMGXB3 (HMG-box containing 3)
Synonyms: KIAA0194; SMF; HMGX3
Tractability: PROTAC: ubiquitination databases record sites on it.
Gene: Protein-coding gene on chromosome 5 (150,000,046 to 150,053,142, forward strand). Ensembl gene ENSG00000113716.
Subcellular location: Nucleus
Subcellular location (Human Protein Atlas): Nucleoli
Gene Ontology:
Cellular component: nucleus
Genetic constraint (gnomAD): Loss-of-function variants: 42 observed, 116.38 expected, observed/expected ratio (o/e) 0.36, 90% interval 0.28 to 0.47. The upper end of that interval is the gene's LOEUF score, 0.47, which puts it in group 2 of 6, group 1 being the genes least tolerant of losing a copy. Missense variants: 1,351 observed, 1,632.9 expected, observed/expected ratio (o/e) 0.83, 90% interval 0.79 to 0.87. Synonymous variants: 583 observed, 634.26 expected, observed/expected ratio (o/e) 0.92, 90% interval 0.86 to 0.98.
Homologues: Orthologues: chimpanzee HMGXB3 (99% identical), macaque HMGXB3 (96% identical), dog HMGXB3 (93% identical), rabbit HMGXB3 (90% identical), rat Hmgxb3 (90% identical), mouse Hmgxb3 (89% identical), guinea pig HMGXB3 (88% identical), pig HMGXB3 (81% identical), tropical clawed frog hmgxb3 (58% identical), zebrafish hmgxb3 (41% identical).
Diseases named in the same sentence as HMGXB3 in open-access papers:
HMGXB3 is named in the same sentence as 4 diseases in open-access papers, as found by Europe PMC text mining. Sharing a sentence is not in itself a finding about the gene and the disease. The quoted sentences say what the papers report.
ciliopathy (1 paper, 2019). A genetic disorder of the cellular cilia or the cilia anchoring structures, the basal bodies, or of ciliary function. "Finding members of the Shh pathway in all the DGE lists of ciliopathy genes in our collection makes us confident to predict possible functions for less well-described genes like Zkscan17 and Hmgxb3." (PMID 31243271, 2019).
colitis (1 paper, 2017). Inflammation of the colon. "Our results therefore revealed a key role of DICER/MiR-324-5p/HMGXB3/WASF-2 axis in maintaining the intestinal mucosal barrier, suggesting a new strategy for colitis and colitis associated CRC." (PMID 28915552, 2017). "Furthermore, in DSS induced colitis mouse model, AgomiR-324 by intraperitoneal injection significantly rescued the regulatory effects of Dicer on expressions of Hmgxb3 and Wasf-2 as evidenced by RT-PCR and immunohistochemistry staining." (PMID 28915552, 2017).
schizophrenia (1 paper, 2022). A major psychotic disorder characterized by abnormalities in the perception or expression of reality. "Although no study has reported the association between HMGXB3 and the treatment response of antipsychotics or schizophrenia, this missense variant can affect the function of transcription factors which play an important role in transcription." (PMID 35484098, 2022).
neoplasia (1 paper, 2022). "Eighth, the HMG-Box Containing 3 gene (HMGXB3), which has been described to be involved in cellular proliferation in neoplasia, has also been reported to be of great interest in meat production." (PMID 35454235, 2022).